INS (insulin)
Diseases named in the same sentence as INS in open-access papers (continued):
Sharing a sentence is not in itself a finding about the gene and the disease.
diabetes (continued). "Defective insulin secretion underlies diabetes mellitus, which is a metabolic disorder characterized by elevated blood glucose levels." (PMID 33802289, 2021). "Diabetes has been shown to promote muscle catabolism due to decreasing insulin signaling and increasing insulin resistance, thereby causing a rapid loss of muscle strength and mass." (PMID 34371843, 2021). "Cell division cycle 42 (Cdc42), a small GTPase of the Rho family, can regulate insulin secretion and diabetes-associated diseases such as diabetic nephropathy (DN) and diabetic foot." (PMID 34447414, 2021). "These minerals’ beneficial role was recognized; magnesium reduced diabetes and IR risk by stimulating insulin secretion by regulating ATP-sensitive potassium channels and the voltage-dependent calcium channels." (PMID 33499915, 2021). "Collectively, our outcomes support the use of lifestyle interventions, such as resistance exercise, to both improve insulin secretion and prevent beta-cell loss in the face of harmful conditions, as in diabetes." (PMID 33883630, 2021). "In adults with T1D, both aging and longer diabetes duration are associated with greater insulin requirements, which can make the creation of safety recommendations around excise more challenging in this population." (PMID 34444464, 2021). "NAFLD is associated with decreased insulin sensitivity, and cohort studies showed that fatty liver increased the incidence of diabetes." (PMID 34579016, 2021). "Hyperglycemia is a feature of diabetes mellitus caused by insufficient insulin secretion or insulin resistance." (PMID 33428669, 2021). "First, we found that retinal insulin concentration remains constant during feeding and fasting and during insulin-deficient diabetes induced by streptozotocin." (PMID 33915127, 2021). "The term “diabetes mellitus”, commonly known as “diabetes”, defines a group of metabolic disorders resulting from deficiencies in insulin secretion, action, or both." (PMID 34681797, 2021). "This study demonstrated the genetic susceptibility of women with a history of GDM to impaired insulin secretion and sensitivity and, ultimately, to diabetes development." (PMID 34801028, 2021). "Diabetes is a group of chronic and metabolic diseases that are caused by defects in insulin secretion or insulin function." (PMID 34568732, 2021). "Overall, the current literature indicate that Dendrobium polysaccharides can restore the metabolic disorders caused by diabetes by repairing islet cell function, improving insulin resistance, and inhibiting oxidative stress and pro-inflammatory cytokines." (PMID 35155528, 2021). "The risk allele of rs17712208 disrupts HNF1B binding, decreases H3K27ac, and reduces the expression of PROX1, leading to impaired β cell insulin secretion and thereby increasing susceptibility to diabetes." (PMID 33919522, 2021). "We identified alternative splicing events in islets of diabetes-susceptible mice amongst others in genes linked to insulin secretion, endocytosis or ubiquitin-mediated proteolysis pathways." (PMID 34445304, 2021). "Lack of cell–cell interaction influences transplantation outcome and diabetes reversion in this work, with deficient insulin secretion is unable to control hyperglycaemia." (PMID 34834340, 2021). "Diabetes mellitus (DM) is a chronic metabolic disease characterized by persistent hyperglycemia caused due to decreased insulin production or impaired insulin activity." (PMID 34213618, 2021). "Pain associated with insulin injection was found in turn to severely impact the ability to self-manage diabetes, inducing patients to avoid or reduce blood glucose monitoring and insulin injections and thus worsening adherence to insulin therapy." (PMID 33777869, 2021). "Among the patients with documented reasons for discontinuation of insulin, the most common reasons were improving blood glucose control, achieved weight loss and initiation of non-insulin diabetes medications." (PMID 33402226, 2021).
diabetes (continued). "Diabetes mellitus is a disease characterized by the body’s inability to produce or properly respond to insulin which ultimately causes elevated blood glucose levels." (PMID 34639171, 2021). "Type 1 diabetes mellitus (T1DM) is an autoimmune disease characterized by absolute or near complete loss of insulin secretion and type 2 diabetes mellitus (T2DM) is characterized by decreased insulin sensitivity and relative insulin deficiency." (PMID 35069149, 2021). "IGF2BP1 can interact and process the IGF2 transcripts, and its dysfunction was associated with tumorigenesis, drug resistance, and diabetes as well as insulin control." (PMID 34203267, 2021). "Two types of diabetes are mainly known: the type 1 which is related to the deficiency of insulin and type 2 that has a direct relation with insulin resistance." (PMID 34258287, 2021). "The current study shows that RYGB preserves β-cell mass and prevents or slows the progression toward the insulin-deficient state, thereby preventing the development of overt diabetes in genetically modified prediabetic mice." (PMID 34673835, 2021). "A phenotype characterized by both high WC and high TyG index has been associated consistently with abnormal glucose and insulin metabolism, with a potential for timely detection of diabetes and more personalized interventions." (PMID 34790686, 2021). "Type 1 Diabetes Mellitus (T1DM) is an autoimmune disorder originated by the loss of tolerance towards components of insulin-producing pancreatic beta cells in genetically predisposed subjects." (PMID 33889155, 2021). "Akita causes an autosomal-dominant form of diabetes, mutant INS- gene-induced diabetes of youth (MIDY)." (PMID 34467852, 2021). "The main findings of this study are 1) TIP-1 mice expressing PIns1 in the APCs show significantly reduced incidence of diabetes, which is associated with reduced insulitis and insulin autoantibody (IAA) expression." (PMID 33841427, 2021). "Referral for CAG due to suspected ACS, insulin treatment, and duration of diabetes were all associated with poor prognosis after the examination." (PMID 33478504, 2021). "Insulin ensures a normal glucose level in blood, and any dysfunction in its production or action causes a serious disease called diabetes mellitus." (PMID 34372300, 2021). "Type 2 diabetes mellitus (T2D) is characterized by a dysfunction in glucose, lipid, and protein metabolism caused by a combination of impaired insulin secretion and insulin sensitivity, resulting in overt hyperglycemia." (PMID 34943836, 2021). "It is well known that high adiponectin serum levels facilitate insulin sensitivity, while reduced adiponectin serum levels are associated with hypertension, dyslipidemia, and type 2 diabetes mellitus." (PMID 33839992, 2021). "The D-FISQ and its variant, the DFIQ, were used among patients with diabetes or kidney failure, as a validated measure of fear of injection and or self-testing associated with insulin or dialysis therapies." (PMID 34111207, 2021). "Type 2 diabetes mellitus (T2DM) is characterized by the inability of the pancreatic β cell to produce enough insulin to maintain glycemic control due to increased insulin demand caused by insulin resistance." (PMID 33546200, 2021). "Diabetic biomarker panel profiling revealed substantially higher levels of proteins linked to diabetes including C-peptide, insulin and leptin in the peripheral circulation of the sampled urban population." (PMID 34361920, 2021). "Type 1 diabetes mellitus is a chronic disease where the combination of genetic predisposition and environmental factors induce β-cell autoimmunity, which leads to insulin depletion." (PMID 33981655, 2021). "Thiazolidinediones or glitazones (TZDs) represent established drugs that treat insulin resistance in type 2 diabetes mellitus, which is a chronic metabolic disorder caused by defects in insulin secretion and insulin action." (PMID 33670968, 2021).
diabetes (continued). "Diabetes mellitus characterized by hyperglycemia is a major chronic metabolic disorder primarily caused by defects in insulin secretion, insulin action or both." (PMID 33413392, 2021). "As a complicated metabolic disease, diabetes mellitus is a characteristic of elevated blood glucose due to insulin secretion and/or deficiency." (PMID 34257700, 2021). "Insight into folding mechanisms of proinsulin has been provided by analysis of dominant diabetes-associated mutations in the human insulin gene (INS)." (PMID 34659132, 2021). "With increasing use of nutritional supplements resulting in weight gain, it is likely that altered body composition will affect glucose metabolism and insulin function and hence risk of diabetes among people with HIV on ART." (PMID 34657634, 2021). "Mechanisms regulating stimulus-secretion coupling have been more extensively studied in beta cells, as the perturbation of insulin secretion is associated with diabetes." (PMID 33367617, 2021). "For example, in subjects with pre-diabetes, reversion to normal glucose values, even temporarily, was associated with a marked delay in the incidence of diabetes, as well as improved beta-cell function and increased insulin sensitivity." (PMID 33910583, 2021). "In the present study, we examined effects of resveratrol on some parameters related to insulin signaling, and also on diabetes-associated dysregulation in Goto-Kakizaki (GK) rats with congenital type 2 diabetes." (PMID 33671110, 2021). "Diabetes mellitus (DM) is a chronic disease with the volatility of hyperglycemic state caused by the deficiency of insulin secretion or the damage of its biological function, or both." (PMID 34796200, 2021). "Diabetes is a worldwide health concern characterized by elevated blood glucose levels caused by inadequate pancreatic insulin synthesis and/or decreased insulin sensitivity." (PMID 34660113, 2021). "Diabetes causes loss of muscle strength and mass, promoting muscle catabolism due to decreasing insulin signaling and increasing insulin resistance." (PMID 34371843, 2021). "Diabetes mellitus (DM) is one of the severe metabolic diseases caused by biological dysfunction of insulin." (PMID 35432808, 2021). "Use of combined oral contraceptive induces significant increases in both fasting blood glucose and insulin levels; this establishes the fact that the continuous use of this contraceptive predisposes to type 2 diabetes mellitus and cardiovascular dysfunctions." (PMID 34938803, 2021). "Diabetes refers to any group of metabolic diseases characterized by high blood sugar and generally thought to be caused by insufficient production of insulin, impaired response to insulin." (PMID 33578512, 2021). "Diabetes can also be caused by a combination of low insulin production as well as low insulin sensitivity or be due to hormonal dysregulation in pregnancy." (PMID 33686454, 2021). "Serum glucose was found to be positively associated with liver cancer (OR 1.88); serum insulin and diabetes were associated with a higher risk of liver cancer mortality (OR 3.42 and 2.95, respectively)." (PMID 34831299, 2021). "Parkinson's disease is another neurodegenerative disorder closely associated with diabetes, sharing pathophysiological mechanisms such as insulin dysregulation, amyloid deposition, microglial activation, and mitochondrial dysfunction." (PMID 34746262, 2021). "The relationship between diabetes and endometrial cancer risk has been modulated by insulin and insulin growth factor (IGF) levels, which are likely affected by the DRRD." (PMID 34444790, 2021). "Our observational study demonstrates that insulin requirements in patients with severe COVID‐19 are associated with severity of respiratory failure and pre‐existing diabetes." (PMID 34268452, 2021). "Our results confirm that there is a high correlation between leptin, TNF-α, and insulin and these correlations cause many disorders in people with diabetes." (PMID 34039404, 2021).
diabetes (continued). "In the pathogenesis of Western medicine, diabetes is a metabolic disease characterized by hyperglycemia due to a deficiency in insulin secretion or insulin dysfunction." (PMID 34692849, 2021). "Diabetes mellitus is an umbrella term that includes multiple metabolic disorders that involve insulin resistance and/or deficient insulin secretion, it is characterized by high levels of blood glucose." (PMID 33804600, 2021). "A recent meta-analysis found positive associations between PRAL scores and SBP, DBP, insulin concentrations, and diabetes." (PMID 34511069, 2021). "The MD has also been shown to modulate glucose and lipid metabolism, improving insulin sensitivity and blood lipid profile, and to reduce the risk for hypertension, diabetes, or cardiovascular disease, risk factors for cognitive decline and dementia." (PMID 33671575, 2021). "GIP is the main incretin hormone in healthy people, causative of most the incretin effects, but the insulin response after GIP secretion in type 2 diabetes mellitus (T2DM) is strongly reduced." (PMID 34819089, 2021). "eGDR, HbA1c, BMI, age, diabetes duration, and insulin requirements were significantly associated with fibrinogen, TF activity, and PAI-1 concentrations, with eGDR providing the strongest association across the range of thrombotic biomarkers." (PMID 33730349, 2021). "Chickens have less insulin sensitivity than mammals and are naturally insulin resistant, but lack the pathologies associated with this resistance (i.e., diabetes) that are exhibited by mammals." (PMID 33572831, 2021). "In fact, stimulating high-glucose-dependent insulin secretion is a much better strategy for treating diabetes, as it is associated with a significantly lower risk of hypoglycemia, a very serious clinical problem in diabetes treatment." (PMID 34556670, 2021). "Diabetes therapy and insulin treatment status, which are positively associated with various forms of self-monitoring and especially with SMBG, were not available with sufficient extent within the present survey." (PMID 33740024, 2021). "A delayed peak time in OGTT in humans is associated with diabetes, increased HbA1c and decreased insulin sensitivity and secretion." (PMID 34444683, 2021). "Complications of diabetes, malabsorption, associated endocrinopathies (for example, primary hypoadrenalism), factitious use of insulin, and psychological factors can predispose to hypoglycemia." (PMID 34583764, 2021). "In the context of type 2 diabetes, elevated levels of serum ferritin were associated with an increased risk of diabetes and were significantly associated with elevated levels of insulin, glucose, and HbA1c." (PMID 34836234, 2021). "Diabetes mellitus (DM), a metabolic disorder characterized by hyperglycemia induced by insulin secretion deficiency and/or resistance to its action, affects more than millions of people across the world." (PMID 34367469, 2021). "Handgrip strength (HGS), as a simple anthropological measurement and an indicator of upper body muscle strength, is considered to be related to insulin action and the risk of the onset and death of diabetes." (PMID 34325672, 2021). "Diabetes mellitus (DM) is a chronic disease associated with carbohydrate metabolism and caused by a deficiency in insulin secretion or by the ineffectiveness in insulin action." (PMID 34371651, 2021). "At least 70 INS mutations in the coding region of the proinsulin domain have been reported to cause mutant INS gene induced diabetes of youth (MIDY)." (PMID 35069438, 2021). "The causal mechanism involved in the onset and progression of diabetes in association with vitamin D likely concerns the role of the vitamin in the immune system and insulin secretion." (PMID 33391906, 2021).
diabetes (continued). "The present systematic review with meta-analysis suggests a beneficial role of Mg supplementation compared to placebo in improving glucose parameters in diabetic patients, as well as glucose and insulin sensitivity markers in subjects at high risk of diabetes." (PMID 34836329, 2021). "Iron is essential for insulin secretion, yet its accumulation is an important determinant of pancreatic islet inflammation and is considered a biomarker of diabetes risk and mortality." (PMID 34831062, 2021). "Obesity associated type 2 diabetes mellitus is a chronic disorder that prevents insulin from being used by the body the way it should." (PMID 33902539, 2021). "Diabetes mellitus induction leads to decreased number and size of the islets, leucocyte infiltration, and β cell degranulation, caused by insulin depletion; it can decrease cell mass as well." (PMID 34577555, 2021). "Several reports have suggested that COVID-19 is associated with the occurrence of insulin-deficient forms of diabetes, raising the possibility that SARS-CoV-2 produces acute β cell dysfunction." (PMID 34241597, 2021). "Increasing liver glycogen corrects many of the metabolic disturbances associated with insulin-deficient diabetes, and most importantly, it does so independently of the levels of circulating insulin." (PMID 33667544, 2021). "By contrast, type 2 diabetes mellitus is characterized by progressive loss of β-cell insulin secretion, which usually occurs in the context of insulin resistance." (PMID 34301918, 2021). "Insulin causes glucose to fall, but in individuals with diabetes, insulin levels are reduced due to auto-immune damage to the pancreatic β cells (type 1 diabetes) or a combination of impaired insulin secretion and action (type 2 diabetes)." (PMID 34814734, 2021). "It was demonstrated that the injection of both miRNAs leads to the downregulation of the Cip/Kip family, which, in turn, improves hyperglycemia in insulin-deficient diabetes mice." (PMID 34959658, 2021). "Type 2 diabetes mellitus (T2DM) often develops as a result of insulin resistance along with a gradual loss of insulin secretion by beta cells of islets of Langerhans." (PMID 34041870, 2021). "Mouse and pig Akita models have been generated to mimic MIDY in humans, both of which develop insulin-deficient diabetes." (PMID 34943844, 2021). "Type 1 diabetes results from the β-cell destruction leading to deficiency of insulin, and then high glucose in blood cannot get into cells, resulting in various symptom of diabetes." (PMID 34684679, 2021). "FoxOs are critical mediators of insulin action on transcription in liver and have been shown to play a role in muscle atrophy associated with diabetes and loss of IR and IGF1R." (PMID 35185597, 2021). "Destruction of β‐cells in pancreas causes deficiency in insulin production that leads to diabetes in the human body." (PMID 33780148, 2021). "Diabetes mellitus is characterized by the body’s inability to control blood glucose levels within a physiological range due to loss and/or dysfunction of insulin producing beta cells." (PMID 33776933, 2021). "In a large, multiethnic study conducted in Dallas, galectin-3 was associated with diabetes prevalence and incidence, possibly through the inflammatory pathway contributing to B-cell fibrosis and impaired insulin secretion." (PMID 34096884, 2021). "An impaired production and/or functioning of insulin causes an increase in blood glucose level (hyperglycaemia) and leads to a metabolic disorder, Diabetes mellitus." (PMID 34869218, 2021). "Diabetes is a group of diseases characterised by hyperglycemia, caused by a defect in the action of insulin, the secretion of insulin, or a combination of both." (PMID 34150671, 2021). "A reduced insulin clearance has been recently identified as a major pathogenetic mechanism of diabetes progression and is typically associated with insulin-resistance, visceral obesity, and non-alcoholic fatty liver disease." (PMID 33919503, 2021).